CNR1 (cannabinoid receptor 1)
Diseases named in the same sentence as CNR1 in open-access papers (continued):
Sharing a sentence is not in itself a finding about the gene and the disease.
schizophrenia (90 papers, 2007 to 2025). A major psychotic disorder characterized by abnormalities in the perception or expression of reality. "An increasing body of evidence has emphasized the role of CNR1 in the genetic underpinnings associated with schizophrenia." (PMID 39457583, 2024). "It has been suggested that CNR1 mediates the relationship between environmental risk factors and changes in brain structure and cognitive function in schizophrenia." (PMID 39457583, 2024). "At the molecular level, studies have shown susceptibility to schizophrenia with certain alleles or genotypes in the CNR1 gene." (PMID 39796008, 2024). "Some genetic studies have linked polymorphisms in the CNR1 gene with an increased risk of schizophrenia." (PMID 37185752, 2023). "In this sense, some studies have associated the gene encoding for the CB1R (CNR1 gene) with the risk for schizophrenia, with the performance in various cognitive dimensions, such as executive function, attention or memory, and with changes in brain volumes." (PMID 37108689, 2023). "A decrease in the mRNA level of cannabinoid receptor 1 (CB1) in the PFC of schizophrenia subjects was associated with the DNA methylation level of the CNR1 gene-encoded CB1 receptor." (PMID 36833173, 2023). "Cnr1 methylation pattern is recurrently found altered in a variety of situations, such as diet, patients with schizophrenia, and THC consumption; Cnr1 is also susceptible to demethylation by the agent 5-aza-2-deoxycytidine." (PMID 37520658, 2023). "Decreased mRNA expression of CB1 receptor encoded by the CNR1 gene has been reported in the DLPFC of patients with schizophrenia." (PMID 35859599, 2022). "Genetic variants in CNR1 have been reported to influence the clinical presentation of schizophrenia in patients exposed to cannabis." (PMID 32433545, 2020). "Using a convergent functional genomics approach, the CNR1 gene encoding CB1R has been identified as a genetic factor involved in vulnerability to the development of schizophrenia." (PMID 33261012, 2020). "A variety of CNR1 polymorphisms have been studied for associations with schizophrenia, with mixed results." (PMID 27323834, 2016). "The CB1R gene (CNR1) maps to chromosome 6q14-15 and linkage studies have suggested a schizophrenia-susceptibility locus lies in this region." (PMID 27323834, 2016). "A significant association between a human CNR1 gene polymorphism and a subtype of schizophrenia has been reported." (PMID 22558109, 2012). "The promoter region of the cannabinoid receptor 1 (CNR1) gene, encoding the type 1 cannabinoid receptor, exhibited hypomethylation in the prefrontal cortex and peripheral blood mononuclear cells (PBMCs) of schizophrenia patients compared to control groups." (PMID 39678047, 2024). "The involvement of certain CNR1 polymorphisms in schizophrenia has been investigated." (PMID 35563156, 2022). "Similarly, enhanced Cnr1 gene expression in PFC was associated with reduced DNA methylation at the Cnr1 gene promoter in a well-validated animal model of schizophrenia (prenatal methylazoxymethanol acetate exposure in rats) and in schizophrenic patients." (PMID 36358910, 2022). "The possible association between CNR1 polymorphisms and schizophrenia has been explored." (PMID 32395111, 2020). "In addition, an association has been observed between the CNR1 gene and the metabolic syndrome in 407 patients with schizophrenia." (PMID 32695035, 2020). "However, the current state of the literature does not suggest that this polymorphism would be a vulnerability factor for hebephrenic schizophrenia and further studies are needed to confirm CNR1 polymorphisms as a genetic risk for hebephrenic schizophrenia." (PMID 25426017, 2014). "Furthermore, CNR1 genetic polymorphisms were associated with WM brain volume variation among schizophrenia patients." (PMID 22907121, 2013).
schizophrenia (continued). "In addition to allelic variations in CNR1 gene, other polymorphic variants and genetic factors have been linked to a different vulnerability for the role of cannabis in schizophrenia." (PMID 27713377, 2010). "Thus, the authors proposed that the G allele of CNR1 rs1049353 polymorphism could represent a “psychopharmacogenetic” biomarker to take into consideration for the treatment of schizophrenia." (PMID 32395111, 2020). "Furthermore, several reports have found that polymorphisms within CNR1 are associated with white matter brain volumes, which might represent a gene × environment relationship for the brain volume deficits in schizophrenia." (PMID 25077169, 2014). "Inconsistencies have been observed regarding changes in the expression of the CNR1 gene, encoding the Cannabinoid Receptor Gene 1 (CB1), in patients with schizophrenia and cannabis users." (PMID 39406996, 2025). "A decrease in both CNR1 mRNA and the receptor levels has been reported in patients with schizophrenia." (PMID 37185752, 2023). "A higher frequency of single nucleotide polymorphisms (SNP) of the CB1r gene (CNR1) was found in patients with MDD and schizophrenia." (PMID 38069051, 2023). "THC or ethanol use was associated with dysregulated expression of CNR1 in the PFC of patients with affective disorder, and the expression of CNR1 was significantly upregulated in the PFC of schizophrenia patients who completed suicide." (PMID 35859599, 2022). "THC or ethanol are each significantly associated with dysregulated expression of CNR1 in the PFC of patients with affective disorder, and the expression of CNR1 is significantly upregulated in the PFC of schizophrenia patients who completed suicide." (PMID 32433545, 2020). "The expression of the CNR1 gene in DLPFC significantly increased in the patients with schizophrenia who had completed suicide (p = 0.01, FDR = 0.07)." (PMID 32433545, 2020). "Our finding of decreased CNR1 expression in schizophrenia replicates and extends findings from previous studies." (PMID 32433545, 2020). "In short, in examining three brain regions from one of the largest postmortem cohorts to date, our study has observed lower expression of CNR1 in DLPFC of patients with schizophrenia." (PMID 32433545, 2020). "The hippocampi of schizophrenia-like brains that were treated with the cannabinoid receptor-1 inverse antagonist AM251 expressed H3K9ac at the level observed in normal brains." (PMID 28300292, 2018). "Autism shared eight highly expressed genes with Schizophrenia, and only two with Epilepsy (Dcx and Cnr1)." (PMID 21935439, 2011). "Schizophrenia subjects show a decrease in Cnr1 mRNA and protein levels in the prefrontal cortex, as well as diminished parvalbumin mRNA in the same region." (PMID 22103416, 2011). "Furthermore, CNR1 expression was significantly decreased in the DLPFC of patients with schizophrenia and major depressive disorder, suggesting that ECS dysregulation is involved in the pathology of these psychiatric conditions." (PMID 39594623, 2024). "Regarding brain imaging phenotypes, some studies report that cannabis use, in the context of specific CNR1 genotypes, may contribute to brain volume differences, both in patients with schizophrenia and healthy volunteers." (PMID 37108689, 2023). "Cannabinoid receptor 1 (CNR1) and leptin gene (LEP) may also be associated with weight gain in schizophrenia patients treated with first and second generation antipsychotics." (PMID 36983567, 2023). "On the other hand, the triplet repeat (AAT)n polymorphism near the CNR1 gene has been examined in the Afro-Caribbean population among cocaine dependents, with schizophrenia or not." (PMID 35327588, 2022). "On the other hand, Tsai and colleagues suggested that the (AAT)n triplet repeat in the CNR1 gene promoter region was not involved in the pathogenesis of schizophrenia, whereas it was significantly associated with the disorganized subtype of schizophrenia." (PMID 35563156, 2022).
schizophrenia (continued). "Additionally, enhanced CNR1 expression was observed in PFC of schizophrenia patients who had committed suicide." (PMID 36358910, 2022). "Additionally, we have observed decreased mRNA expression of CNR1 in the DLPFC of patients with schizophrenia." (PMID 32433545, 2020). "And last, but not least, we have identified a novel transcript in CNR1, whose expression is associated with a genetic variant that also is associated with increased risk for drug addiction, a major comorbidity in both schizophrenia and affective disorders." (PMID 32433545, 2020). "At the transcript level, the expression of the full-length CNR1 transcript was downregulated significantly in the DLPFC of patients with schizophrenia (p = 8.86E−03, FDR = 0.02), and patients with MDD (p = 1.18E−04, FDR = 7.50E−04), but not in patients with bipolar disorder (p = 0.40)." (PMID 32433545, 2020). "In DLPFC, the expression of CNR1 at the gene level is significantly decreased in patients with schizophrenia (p = 3.31E−04, FDR = 9.92E−04) and patients with MDD (p = 1.67E−04, FDR = 7.50E−04) compared with non-psychiatric controls, but not in patients with bipolar disorder (p = 5.49E−02)." (PMID 32433545, 2020). "In addition genetic studies have shown an association between the gene encoding CB1R (CNR1) and schizophrenia." (PMID 17684555, 2007). "Interestingly, Δ9-THC or ethanol exposure upregulated CNR1 expression in patients with affective disorders, and CNR1 expression was also increased in schizophrenia patients who completed suicide, pointing to the complex interaction between cannabis use, mental health, and suicide risk." (PMID 39594623, 2024). "Short tandem repeats and VNTRs in the cannabinoid receptor 1 (CNR1), glutamate ionotropic receptor NMDA type subunit 2A (GRIN2A), prodynorphin (PDYN), and proenkephalin (PENK) genes were reported to be associated with the vulnerability to schizophrenia and substance dependence." (PMID 35360861, 2022). "The degree of CNR1 DNA methylation in PBMCs may appear a potential biomarker for schizophrenia." (PMID 33776815, 2021). "Additionally, other alterations of CNR1 gene may act as a protective factor for schizophrenia, or induce a better pharmacological response to atypical antipsychotics." (PMID 27713377, 2010). "We have also compared the expression of the CNR1 transcripts in the PFC, hippocampus and caudate among controls, and individuals with either schizophrenia or affective disorders." (PMID 32433545, 2020). "In conclusion, we have found differential expression of CNR1 in PFC and caudate of patients with psychosis, namely schizophrenia, bipolar disorder, and MDD." (PMID 32433545, 2020). "Recently, it was also observed a significant increase in CB1 expression, and a reduction in mechanisms of DNA methylation at the promoter of CNR1, the gene coding for the CB1 receptor in schizophrenia patients." (PMID 29311804, 2017). "Despite selecting two CNR1 variants based on their relevance for SSD and neurodevelopment, the use of two SNPs neither represents the polygenic background of schizophrenia and SSD nor the whole genetic determinants of dermatoglyphic configurations." (PMID 39457583, 2024). "The endocannabinoid system is hypothesized to contribute to psychotic symptoms, and the Cannabinoid Receptor 1 (CNR1) gene, which codes for endocannabinoid receptors, has been investigated for its possible links to schizophrenia." (PMID 36980961, 2023). "By linear regression, the expression of the CNR1 gene is marginally decreased in the DLPFC of the patients with schizophrenia (p = 1.61E−02, FDR = 4.83E−02), but not in patients with bipolar disorder (p = 5.19E−02) or MDD (p = 0.81)." (PMID 32433545, 2020). "The expression of the truncated CNR1 transcript was not significantly altered in the DLPFC of patients with schizophrenia (p = 0.62), bipolar disorder (p = 0.67) and MDD (p = 0.09)." (PMID 32433545, 2020).
schizophrenia (continued). "Furthermore, the expression of CNR1, the gene coding for the CB1 receptor, was found to be up-regulated in the peripheral blood of schizophrenia patients." (PMID 32695035, 2020). "However, the schizophrenia-like traits in the hippocampus were somewhat suppressed by cannabidiol (CBD) or AM251, a cannabinoid receptor-1 inverse agonist." (PMID 28300292, 2018). "Furthermore, individuals with schizophrenia who are receiving treatment with first- and second-generation antipsychotics may gain weight due to genes like leptin (LEP) and cannabinoid receptor 1 (CNR1)." (PMID 40676294, 2025). "Recognizing that most schizophrenia patients have no prior marijuana use, and most adolescents who abuse marijuana do not develop schizophrenia, the link spurred investigations into the impact of genetic variation in the cannabinoid receptor 1 (CNR1)." (PMID 25077169, 2014). "However, marijuana use alone is unlikely to cause schizophrenia; rather, it may act as a trigger in individuals who are genetically predisposed, e.g., those carrying variants in their catecholamine-O-methyltransferase (COMT) gene or in their CB1R gene CNR1." (PMID 39594623, 2024).
Insulin resistance (76 papers, 2009 to 2026). Increased resistance towards insulin, that is, diminished effectiveness of insulin in reducing blood glucose levels. "In this study we aim to investigate if CNR1 is a factor associated with the development of insulin resistance in adipose tissue by the examination of the endocannabinoid system in freshly harvested SAT from healthy control vs. T2D subjects." (PMID 27858284, 2017). "Although subsequent studies reported that CNS-specific Cnr1 deficiency alone prevented HFD-induced hepatic steatosis, insulin resistance, and dyslipidemia, recent data indicate that peripherally restricted Cnr1 antagonists can indeed prevent this metabolic syndrome." (PMID 26082754, 2015). "However, whether CNR1 overexpression is a cause or a result of insulin resistance remains to be determined." (PMID 27858284, 2017). "Cannabinoid receptor 1 (CB1R) activation exacerbates insulin resistance and hyperglycemia by inducing endoplasmic reticulum stress and gluconeogenesis." (PMID 40959483, 2025). "More and more evidence shows that cannabinoid receptor 1 (CB1) is a key mediator of insulin resistance and liver lipogenesis." (PMID 38397045, 2024). "In this study we show that CNR1 gene expression is elevated in states of insulin resistance and T2D." (PMID 27858284, 2017). "Our findings also imply that subjects with elevated insulin resistance have less elevation of CNR1 gene expression by glucocorticoids compared with insulin sensitive subjects, possibly due to the already elevated levels of CNR1 in insulin resistance states." (PMID 27858284, 2017). "Here we explore the role of peripheral CNR1 in states of insulin resistance in human adipose tissue." (PMID 27858284, 2017). "Our data demonstrate that CNR1 and the endocannabinoid system in human adipose tissue is upregulated in states of insulin resistance, including T2D and glucocorticoid exposure." (PMID 27858284, 2017). "Cannabinoid receptor 1 antagonism has demonstrated promising effects with increased resistance to hepatic steatosis, reversal of hepatic steatosis, and improvements in glycemic control, insulin resistance, and dyslipidemia." (PMID 29843404, 2018). "CNR1 is upregulated in states of type 2 diabetes and insulin resistance." (PMID 27858284, 2017). "Additionally, gene expression levels of CNR1 and endocannabinoid-regulating enzymes from both groups correlated with markers of insulin resistance." (PMID 27858284, 2017). "Besides being involved in the cannabinoid-induced central nervous system (CNS) effects, cannabinoid receptor 1 (CNR1) participates in the development of insulin resistance in the human skeletal muscle and its expression is markedly decreased in AD brains." (PMID 21726470, 2011). "In addition, CNR1 is expressed in adipose tissue and might be involved in insulin resistance." (PMID 37373173, 2023). "In addition, we aim to, via glucocorticoid-induced insulin resistance by long-term incubation (24 h) of SAT; investigate whether CNR1 plays a role in the regulation of glucose and lipid metabolism in human adipocytes." (PMID 27858284, 2017). "We show that after 24 h incubation with no additional treatments, CNR1 gene expression in both adipose tissue depots is positively correlated with several parameters of insulin resistance and central obesity (e.g., HOMA-IR, BMI, waist circumference and fat cell diameter)." (PMID 27858284, 2017). "Interestingly, in humans, CnR1 participates in the negative crosstalk between fat and keletal muscle cells, and recent data suggest it may play a role in the development of insulin resistance." (PMID 26086818, 2015).
metabolic syndrome (71 papers, 2010 to 2025). A cluster of metabolic risk factors for CARDIOVASCULAR DISEASES and TYPE 2 DIABETES MELLITUS. "This study aimed to analyze the association between polymorphism rs12720071 of the cannabinoid type 1 receptor (CNR1) gene with dyslipidemia and overweight in young, healthy Mexicans." (PMID 31723535, 2019). "Genetic variability in the CB1 receptor itself (gene name CNR1) is also associated with dyslipidemia." (PMID 21209828, 2010). "GC can act through the peripheral stimulation of the cannabinoid receptor 1 (CB1R) in the liver, inducing hepatic lipogenesis, steatosis, and dyslipidemia." (PMID 38397000, 2024). "Among the genes with the strongest relationship with metabolic syndrome, CNR1—cannabinoid receptor 1 gene, LEP—leptin promoter gene, FTO—alpha-ketoglutarate-dependent dioxygenase gene, MC4R—melanocortin 4 receptor gene and VDR—vitamin D receptor stand out." (PMID 32272684, 2020). "While hepatocyte-specific CNR1 knockout mice gain weight at a rate similar to their wild type littermates, they are resistant to dyslipidemia in a manner comparable with a lean phenotype." (PMID 21209828, 2010). "Interestingly, the novel cannabinoid receptor-1 (CB1R) inverse agonist, INV-202/monlunabant in subjects with metabolic syndrome causes a remarkable reduction in body weight and improvement in the cardiometabolic profile without adverse effects." (PMID 39407846, 2024). "Finally, a synthetic GC was shown to up-regulate peripheral CNR1 expression, suggesting it is involved in GR-regulated lipolysis making it an attractive drug target in type 2 diabetes and dyslipidemia." (PMID 33401515, 2021). "We report a CNR1 haplotype (21.1% frequency in subjects of Northern European ancestry) that may protect against the development of low-HDL dyslipidemia during weight gain." (PMID 21209828, 2010). "Peripheral CNR1 could be an interesting drug target in type 2 diabetes and dyslipidemia." (PMID 27858284, 2017).